HIF1A (hypoxia inducible factor 1 subunit alpha)
Diseases named in the same sentence as HIF1A in open-access papers (continued):
Sharing a sentence is not in itself a finding about the gene and the disease.
tumor (continued). "HIF‐1α can also induce TAMs to secrete IL‐23, which activates the proliferation of regulatory T cells (Tregs), promotes the expression of IL‐10 and TGF‐β, and thus inhibits the capacity of cytotoxic lymphocytes to kill tumor cells." (PMID 36703877, 2023). "HIF-1α is one of the critical transcription factors involved in metabolic reprogramming through glucose transport, glycolysis, the PDH complex, and the TCA cycle in tumor cells." (PMID 38435444, 2023). "HIF-1α is known to play an important role in hypoxia-induced angiogenesis, metastasis, EMT and invasion of cancer cells, and also in inducing conventional drug-resistant properties, thus playing a central role in tumor cell malignancy." (PMID 37583906, 2023). "In summary, the present study indicated that TH-302 NPs could reduce the expressions of PD-L1 and HIF-1α, promote CD8+ T-cell infiltration in tumour tissues and enhance the efficacy of α-PD-1 immunotherapy by alleviating the hypoxic microenvironment." (PMID 37993847, 2023). "Since hypoxia is a common feature of solid tumors, the correlation between HIF‐1α and NAT10 may provide a clear explanation for the substantial enrichment of NAT10 in multiple tumor tissues." (PMID 37328448, 2023). "It has been reported that HIF-1α can activate VEGFA and promote tumor angiogenesis." (PMID 37239383, 2023). "In addition to Hif1a and Vegfa upregulation, MDM-B showed differential expression of Mmp12, Mmp14, and Igf1, which were also part of the tumor microenvironment pathway." (PMID 37858232, 2023). "Interestingly, FBXO28 is found to exert either oncogenic or tumor suppressing functions by targeting MYC, SMARCC2 or HIF-1α, under different cellular contexts, complicating its role in tumorigenesis and metastasis." (PMID 37596321, 2023). "Meanwhile, an in vivo study showed that 30 and 60 mg/kg wogonin could significantly reduce the tumor weight of male BALB/c nude mice, and decreased the expression of HIF-1α, glycolysis-related proteins, and PI3K/AKT." (PMID 37693915, 2023). "Hence, bLF specifically suppressed tumor angiogenesis through p-p65 inhibition by binding to TRAF6 and suppressing HIF-1α activation followed by VEGF/VEGFR down-regulation." (PMID 36678795, 2023). "First, the expression of all hypoxia markers and vessel density were significantly different in pT1b compared with those in non‐neoplasia, whereas the expression of HIF‐1α was not significantly different in pTis‐T1a compared with that in non‐neoplasia." (PMID 37329213, 2023). "Our research discovered that HIF1A and ATM are crucial genes in the process of CIH that leads to ferroptosis and that changes in the immunological microenvironment promote the progression of tumor disorders such as THCA." (PMID 36937508, 2023). "There are accumulating data suggesting that HIF1α and HGF may act as pro-tumour factor while TIMP-2 is an anti-cancer regulator." (PMID 35953652, 2023). "Together with the highly hypoxic tumor microenvironment, it is not surprising that we observed a high influx of HIF-1α-expressing neutrophils into the pancreas of OT mice." (PMID 36614196, 2023). "Furthermore, there are various tumor types that have been identified as being NRG1-positive, suggesting that HIF1A and NRG1 have pleiotropic effects on OSA and cancer." (PMID 36831404, 2023). "We studied the expression of PD-L1 in a series of 66 PCs, in parallel with the expression of hypoxia- and acidity-related immunohistochemical markers (Hypoxia-inducible factor HIF1α, and lactate dehydrogenase LDHA) and tumor-infiltrating lymphocyte TIL density." (PMID 37067635, 2023). "The HIF-1α pathway contributes greatly to metabolism alteration via glycolysis stimulation and oxidative phosphorylation (OXPHOS) suppression under hypoxic conditions during tumor development." (PMID 36925652, 2023). "Considering that induction of tumor angiogenesis is known to be strongly related to the presence of hypoxia, we analyzed the expression of HIF-1α in treated and non-treated tumors." (PMID 38201461, 2023).
tumor (continued). "Since the HIF-1α targets, VEGF-A and VEGF-C, are involved in tumor angiogenesis and lymphangiogenesis, we further assessed the effects of everolimus on potential crosstalk between tumor and vascular endothelial and lymphatic cells." (PMID 36745547, 2023). "In the hypoxic tumor microenvironment, the transcriptional regulation of HIF1A mediates the upregulation of PLOD2, which can activate EGFR phosphorylation, thereby activating the downstream AKT-mTOR pathway and ultimately promoting ccRCC tumor progression." (PMID 38008826, 2023). "Hypoxia-inducible factor 1-alpha (HIF-1α) may activate the transcription of genes related to Cu metabolism (e.g., those that control CTR1), contributing to higher Cu levels in hypoxic tumor cells." (PMID 38139406, 2023). "NVP-LAQ824 attenuated tumor growth and angiogenesis and enhanced VEGFR inhibitor PTK787/ZK222584-mediated inhibition of angiogenesis via upregulation of p21 and downregulation of angioprotein-2, Tie-2, VEGF, HIF-1α, and survivin." (PMID 36969235, 2023). "Therefore, it can be concluded that EAA can effectively inhibit the protein expression of HIF-1α, VEGF, and N-cadherin in the HT1080 cells, thus achieving the effect of tumor suppression." (PMID 36976205, 2023). "Rs11549465, rs2057482 in the HIF1A gene did not correlate with the expression of HIF-1α either in the tumor or in the normal kidney." (PMID 38273861, 2023). "The overexpression of HIF-1α has also been observed to induce the epithelial-to-mesenchymal transition (EMT), enabling tumor cells to acquire a mesenchymal phenotype, which facilities invasion, migration, and dissemination from the primary tumor site." (PMID 37345074, 2023). "It was shown that the presence of HIF1α is essential for the formation of tumors, whereas the absence of HIF2α has a limited effect on tumor initiation and growth." (PMID 37190141, 2023). "The 2-day systemic treatments with DFO or DFX were likely not adequate to lower the concentration of iron within the tumor cells to the level necessary to stabilize HIF-1α for induction of Zta synthesis." (PMID 36980731, 2023). "Studies on human cytological specimens revealed that HIF-1α and GLUT-1 were expressed by tumor cells in nearly all cytological cases of ascites, although to different extents, which indicated that human ascites tumors were also in hypoxic state, which is consistent with the results of animal models." (PMID 36620569, 2022). "Hypoxic tumor-resident NK cells can also upregulate VEGFR-1 by overexpressing HIF-1α, thereby inhibiting non-productive VEGF-driven angiogenesis, and promoting HCC growth by generating functional blood vessels." (PMID 35912218, 2022). "Concurrently, HIF-1 induces the expression of DDIT4/REDD1, which in a negative feedback loop impairs mTORC1, HIF-1α accumulation and suppresses tumor growth." (PMID 35406562, 2022). "HIF-1α, in collaboration with c-Myc, promotes glucose uptake by cells and accelerates tumor cell aerobic glycolysis by increasing the expression of GLUTs (primarily GLUT1 and GLUT3) or additional glycolytic enzymes that rely on HIF-1α (such as LDHA, MCT4, and GAPDH)." (PMID 36276846, 2022). "In addition, the upregulation of PTEN, downregulation of HIF‐1α, and finally decreased VEGF expression, promote the normalization of blood vessels in the tumor microenvironment." (PMID 34936240, 2022). "Nevertheless, the effect of HIF‐1α on TIMP‐1 expression seems to be marginal in our case, as HIF‐1α silencing in 3D tumor spheroids did not alter TIMP‐1 at either the RNA or protein level." (PMID 35600659, 2022). "The contents of HIF-1α and VEGF decreased by 34.8% and 39.9%, respectively, compared with the control, suggesting that tumor angiogenesis was inhibited and the hypoxic microenvironment of tumors may be improved by combination therapy." (PMID 36047064, 2022).
tumor (continued). "The hypoxia in the tumor microenvironment may activate the JMJD5/PKM2/HIF‐1α axis, enhancing HIF‐1α transactivation activity, and paving the way for reprograming of cell metabolism." (PMID 35852137, 2022). "Claudin 6 (CLDN6) appears to be able to regulate the HIF-1α pathway through SENP1 in BC cells and BC patients with primary CLDN6 loss are more prone to have tumor metastasis, due to a lack of feedback mechanism that impairs HIF-1α stability." (PMID 35465332, 2022). "SENP1 RNA expression is correlated positively with HIF2α, but not HIF1α, RNA levels in these tumor samples." (PMID 36284084, 2022). "Hypoxia in tumors occurs when new blood vessels can not keep up with tumor growth and leads to the elevation of hypoxia-inducible factor-1α (HIF1α), which plays a vital role in NSCLC cells epithelial-to-mesenchymal transition (EMT)." (PMID 35473752, 2022). "Through correlation analysis, we found that the HIF-1α score was significantly negatively correlated with the ADC value (p = 0.002), tumor tissue hypoxia is an important feature of PDAC, tissue hypoxia is correlated with the degree of malignancy and invasiveness of PDAC." (PMID 36077777, 2022). "In the hypoxic TME, HIF1α binds to the HIG2 promoter and increases the angiogenesis gene VEGFA, and this may encourage tumor resistance to anti-angiogenesis treatments." (PMID 36233088, 2022). "For example, mTOR is a major direct regulator of the Warburg effect, while HIF1α, a downstream mTOR target, is highly expressed and synergizes with c-Myc-hnRNP splicing modulators to enhance PKM2 expression, which, in turn, promotes tumor progression." (PMID 36588722, 2022). "In addition, growing evidence suggests that TTFs inhibits tumor angiogenesis by downregulating VEGF and HIF1α expression." (PMID 36070228, 2022). "And in the hypoxic tumor microenvironment of HCC, CFL1 can be transcriptionally activated by hypoxia-inducible factor-1α (HIF-1α), and subsequently interacts with PLD1 to inhibit PLD1 ubiquitination degradation and stabilize its expression, thereby activating the AKT pathway." (PMID 36463115, 2022). "A substantial increase in the HIF-1α expression observed in OPM-BMG cells in-vitro and tumor tissues compared to BMG-1 may be responsible for promoting proangiogenic pathway and neovascularization." (PMID 36591481, 2022). "The expression of the P2X7 receptor can be induced by elevated HIF-1α under hypoxia, and then P2X7 can phosphorylate ERK and AKT signaling pathways and increase the accumulation of NF-κB, which promotes tumor cell EMT by regulating the expression of MMP2 and MMP9." (PMID 36139386, 2022). "For example, HIF-1α induces various pro-angiogenic factors, such as the vascular endothelial growth factor (VEGF), to develop new blood vessels and increase oxygen and nutrient transport to the tumor." (PMID 36140753, 2022). "Other targets of miR-199a that may affect tumor proliferation and metastasis are ROCK1, HIF1α, BCAM, FZD6, and DDR1." (PMID 36499729, 2022). "In the hypoxic TME, the HIF-1α-mediated transcriptional upregulation of LOX not only increases the expression of ITG-α5 and its ligand fibronectin in tumor cells, but also induces collagen crosslinking and fibronectin assembly, forming the mechanical barrier to prevent drug transport." (PMID 36293126, 2022). "HIF-1α can activate the expression of downstream target gene vascular endothelial growth factor (VEGF), induce tumor cells to generate blood vessels, and bring oxygen and nutrients to tumor cells." (PMID 35311089, 2022). "On the other hand, previous reports suggest the negative effect of HIF-1α for cytokine production and tumor surveillance promotion." (PMID 35769460, 2022). "After being stimulated by hypoxia-inducible factor (HIF-1α), TAMs release a set of angiogenic cytokines, such as vascular endothelial growth factors (VEGF)-A, TGF-β, CXCL12, PDGF, and MMPs, which in turn promote tumor angiogenesis." (PMID 36311793, 2022).
tumor (continued). "Notably, specific m6A regulators act synergistically with HIF-1α and HIF-2α to promote the CSCs phenotype in multiple tumor types." (PMID 35794625, 2022). "Moreover, these channels positively correlate with increased hypoxia-inducible factor-1 alpha (HIF-1α) expression, which drives the vascular mimicry process through the inner tumor mass." (PMID 36553127, 2022). "It has been demonstrated that hypoxia inducible factor (HIF), including HIF-1α and HIF-1β subunits, is a heterodimeric transcription factor which may involve in the tumor angiogenesis and progression." (PMID 35607406, 2022). "A variety of factors in the tumor microenvironment, such as hypoxia and certain metabolites, can regulate the hydroxylase activity of PHD2 to restrain HIF-1α degradation, resulting in augmented HIF-1α protein levels and elevated aerobic glycolysis in cancer cells." (PMID 35903683, 2022). "Notably, lncRNA can be induced to be expressed in a HIF-1α-dependent manner, stimulating the production of EMT transcription factors that regulate EMT development and promote tumor metastasis, invasion, malignant proliferation, and poor prognosis." (PMID 36139386, 2022). "Furthermore, hypoxia/HIF-1α induces the secretion of CXCL12, VEGF, and ANG1/2, leading to vascular changes, such as fragile tumor angiogenesis, through the recruitment of vascular endothelial cells." (PMID 35743281, 2022). "In contrast, if tumor tissue is locally hypoxic, as implied in the HIF-1α immunohistochemical staining for MC-38 and H460 grafts, with many regions of HIF-1α-positive cells, and where hemoglobin is not fully oxygen-saturated before hyperoxic challenge, T1 is expected to be unaffected." (PMID 35804886, 2022). "We therefore hypothesized that HIF-1α is involved in positively regulating YY1 and is the reason for chemoresistance in tumor cells." (PMID 35163649, 2022). "The high HIF-1α expression was observed in the hypoxic tumor microenvironment (TME); thus, specific inhibition of HIF-1α may provide certain benefits in clinical cancer therapy when combined with a multitherapeutic approach." (PMID 35607406, 2022). "Functional studies indicated that Myo1b acts as a pivotal autophagy regulator by modulating the autophagosome-lysosome fusion, which could inhibit the autophagic degradation of HIF-1α, thus enhancing VEGF secretion and then promoting tumor angiogenesis in CRC." (PMID 36347835, 2022). "Immunohistochemistry using Apotome-based sectional illumination showed that in the patient PDAC sample with large tumor mass but no lymph metastasis, many stromal areas had high HIF-1a staining." (PMID 35565326, 2022). "This is likely stimulated by extracellular VEGF that is released by S100A4(+)/HIF-1α(+) tumor cells in non-Ps perinecrotic lesions." (PMID 35392912, 2022). "Hypoxia contributes to the generation of immunosuppressive TME and immunotherapeutic resistance by upregulating HIF-1α signaling pathways and triggering the expression of VEGF, PDGF, and other cytokines, resulting in a modification of tumor metabolism, angiogenesis, and lymphangiogenesis." (PMID 36686754, 2022). "Compared to HIF1A, data on the function of HIF2A in the tumor immune escape mechanism remain limited to date, and it has yet to be determined whether HIF2A may also be an upstream target to act on PD-L1/PD-1." (PMID 35659268, 2022). "As an important regulator of Wnt transduction in the canonical signaling pathway in tumours, Dickkopf-related protein 3 (DKK3) negatively regulates aerobic glycolysis [HK2, HIF-1α, GLUT-1, LDHA and 3-phosphoinositide-dependent protein kinase-1 (PDK-1)] in BxPC-3 cells." (PMID 36578477, 2022). "Indeed, increased production of VEGF has been demonstrated in human PDAC cell lines and resected PDAC tumor tissues, showing that VEGF is produced under the control of activated HIF-1α and STAT3 under conditions of oxygen deprivation." (PMID 36408139, 2022).
tumor (continued). "The heterodimer HIF-1α/HIF-1β binds to the hypoxia-responsive element (HRE) motif found in the promoter of several genes involved in several biological processes that tolerate cellular adaptation to hypoxia and confer a survival benefit to tumor cells." (PMID 35795658, 2022). "Our data show that tumor hypoxia was similar in the tumors grown in Cx37−/− and WT mice, indicating that HIF-1α is unlikely to account for the tumor differences observed in the two types of mice." (PMID 35328350, 2022). "In contrast, both MGMT and HIF-1α had negative expression in all the tumor lesions of the 17 nude rats." (PMID 36591483, 2022). "One recent study has shown that mice immunized by a HIF-1α peptide pool, namely the HIF-1α vaccine, have a higher level of HIF-1-specific IgG in sera, which neutralizes HIF-1α, enhances Th1 and Th2 immunity, and reduces tumor growth in TNBC and activities of BCSCs." (PMID 35805056, 2022). "Albeit, with a great degree of variability, and HIF-1α mRNA-expression did not correlate to tumour characteristics or patient outcome (data not shown)." (PMID 35140341, 2022). "HIF-1α and VEGF are known to play crucial roles in the tumor angiogenic process." (PMID 35198082, 2022). "In HCT116 Cells, wogonin inhibited the expression of HIF-1α and glycolysis-related proteins (HK2, PDHK1, LDHA) by inhibiting the PI3K/Akt signaling pathway, reduced glucose uptake and lactate production to combat drug resistance of tumor cell." (PMID 36339566, 2022). "We further identified a significant positive correlation between MT1JP and the expression of miR-138, and a significant negative correlation between MT1JP and the expression of HIF-1α in tumor tissues." (PMID 35703312, 2022). "AGE/RAGE signaling pathway activates intracellular and downstream HIF-1α and PI3K/AKT signaling pathways to promote tumor cell proliferation, migration, invasion, cloning, and spheroidization, thereby inhibiting cell apoptosis and activating the epithelial-mesenchymal transition process." (PMID 35815259, 2022). "Moreover, SOX17 reduced the irradiation tolerance of ESCC cells by reducing HIF1α expression via the MALAT1-miR-199a axis, and attenuated tumor formation in nude mice." (PMID 35614065, 2022). "Comprehensive analyses of flow cytometry and immunohistochemistry results revealed that bevacizumab treatment enhanced the HIF-1α expression and increased the proportion of CD44+/CD117+ cells, resulting in the tumor recurrence in both the bevacizumab alone and bevacizumab + cisplatin groups." (PMID 36046821, 2022). "Circulating succinate was elevated in patients with head and neck squamous cell carcinoma, along with increased expression of SUCNR1, HIF1α, SDHA and SDHB in the tumor tissue relative to matched normal mucosa, further highlighting a role of succinate as oncometabolite." (PMID 36551845, 2022). "HIF-1α is generally inactivated in normal tissues but frequently stabilized in tumor cells regardless of oxygen tension." (PMID 35239514, 2022). "Moreover, genes which regulate cell death or anaerobic glycolysis appear to be predominantly controlled by HIF-1α, but genes which regulate erythropoietin synthesis (EPO) and tumor stemness or pluripotency are primarily regulated by HIF-2α." (PMID 36003773, 2022). "Besides, the engineered liposomes were found to down-regulate HIF-1α expression and CD31-positive tumor vessels and hence modulate the tumor microenvironment." (PMID 36358663, 2022). "Excessive HIF-1α dominates the maintenance of the tumor microenvironment, and studies have shown that inhibiting HIF-1α-binding protein CDK5 affected HIF-1α activity could effectively suppress the angiogenesis of tumorigenic." (PMID 35163556, 2022). "RUNX2 stabilizes HIF-1α protein for regulating optimal angiogenesis in chondrocytes, but overexpressed RUNX2 in cases of cancer increases VEGF expression and anti-apoptotic activity under hypoxia, resulting in increased tumor progression." (PMID 36231060, 2022).